CCL5 (C-C motif chemokine ligand 5)
Diseases named in the same sentence as CCL5 in open-access papers (continued):
Sharing a sentence is not in itself a finding about the gene and the disease.
tumor (continued). "We further demonstrate that suppression of endothelial CCL5/CCR5 signaling leads to defects in mTOR/AKT pathway activation, as well as vascular and tumor growth defects in vitro and in vivo." (PMID 27863423, 2016). "CCL5 and IGF-1 specific staining was detected in peritumoral adipocytes of TNBC samples (up to 1 cm distance from the tumour)." (PMID 27027351, 2016). "It has been found that adipose tissue MSCs contribute to tumor-promoting state of TME, through increased secretion SDF-1, VEGF, chemokine ligand 5 (CCL5), platelet-derived growth factor D (PDGF-D), and TGF-β in response to presence of tumor cells." (PMID 27630452, 2016). "CDDO-Me also inhibited expression of chemokines that mediate selective recruitment of TAMs and M2 macrophages, (CCL3, CCL4, and eotaxin) and monocytic infiltration of tumor sites (CCL2 and CCL5)." (PMID 26918785, 2016). "Overall, our data indicate that circulating and intratumoral IM are increased in RT-treated tumor-bearing hosts as a result of a radiation specific up-regulation of the monocyte chemokine ligands CCL2 and CCL5." (PMID 27852031, 2016). "Taken together the tumor growth and vascularization defects observed following ablation cancer cell of CCL5, and in CCR5 null mice, strongly support a role for tumor CCL5/host CCR5 paracrine signaling in tumor growth and neovascularization." (PMID 27863423, 2016). "VACV expressing CCL5/RANTES and CXCL11 have both been shown to increase local trafficking of CTLs and reduce tumor volume in virus-treated mouse models." (PMID 28536385, 2016). "Our PCR array data showed that both M1-related genes (Ccl2, Ccl3, Ccl4, Ccl5, Il12b, Il1b and Ccl1) and M2-related genes (Il10, Tgfb2 and Il1rn) were significantly upregulated in NM11-shsST2 tumours compared with NM11-shCont tumours." (PMID 27882929, 2016). "Stimulation of CAFs and MSCs with tumor cell-derived conditioned media leads to upregulation of various chemokines, including CCL2, CXCL8, and CCL5." (PMID 26884646, 2016). "In contrast, CCL5 and CXCL9 showed significantly higher mRNA expression levels and had increased protein levels in the SG-/- tumour tissue." (PMID 27223472, 2016). "Namely, CCL5 released from CRC cells recruits CCR5+ T-reg, which leads to TGF-β-mediated apoptosis of CD8+ CTL and tumor growth by immune escape." (PMID 27136535, 2016). "Although expression of CCL5, CXCL9, CXCL10 and CXCL12 were also consistently detected in the tumours, expression of each was also detected in spleen and lymph node." (PMID 25495686, 2015). "All key molecules in the spleen of tumor bearing old hosts (CD2, CD3ε, CCL19, and CCL5) (also been reported to exist in the spleen) leads to immune cell survival and function through increased T-cell survival and activity." (PMID 26497558, 2015). "We found that efficient knockdown of Ccl5 using two independent shRNA hairpins (P1 and P2) resulted in SCC FAK-WT shRNA-Ccl5 tumor regression by days 21–27." (PMID 26406376, 2015). "Other studies have explored the possibility of using oncolytic vaccinia virus to express chemokines such as CCL5 and CCL19 to enhance the therapeutic effect by increasing T cell and dendritic cell infiltration into tumor tissues." (PMID 25460506, 2015). "Meanwhile, RT-PCR data showed that the expression of CCL5 and CXCL10 was positively correlated with the local expressions of the CD8+ T lymphocyte markers (CD8 and Granzyme B) in tumor tissues." (PMID 26317795, 2015). "Tumor-free induction by PMSB were mostly reversed by IFN-γ or IP-10/CXCL10 blockade and evidently deterred by MIG/CXCL9 or RANTES/CCL5 blockade (P < 0.05 versus controls)." (PMID 26512920, 2015). "It was revealed that the following immune related factors were key factors being commonly up-regulated for old tumor bearing hosts compared to all younger age groups: CD2, CD3ε (or CD3E), CCL19, and CCL5." (PMID 26497558, 2015). "LEC-derived CCL5 recruits CCR5-positive cancer cells into the lymphatic vessels and triggers tumor dissemination." (PMID 26173622, 2015).
tumor (continued). "These genes included tumor markers (MUC16), genes that control tumor migration (MYL9), metastasis (CEACAM6, VEGFC, CX3CL1, CST1, CCL5, S100A9, IGF1, NOTCH3), cell adhesion (FN1, CEACAM1), and inflammation (TRAF2, NF-κB2 and RelB)." (PMID 26090868, 2015). "Statistical analysis of those samples indicated that both CCL5 and CXCL10 expression (IHC scores) was significantly higher in tumor lesions versus marginal tissues (1.878 ± 1.679 vs. 0.588 ± 0.543, p < 0.0001; 2.472 ± 1.997 vs. 1.588 ± 1.042, p < 0.005)." (PMID 26317795, 2015). "Collectively, these results indicate that CCL5 in JDP2 expressing BMDCs is necessary and sufficient for tumor cell invasion." (PMID 26497998, 2015). "Previous studies have shown that myeloid-derived suppressor cells (MDSCs), tumor-infiltrating lymphocytes (TIL), MSCs, CAFs and CSLCs can produce CCL5 and that cancer cells express the CCL5 receptors CCR1, CCR3, and CCR5." (PMID 25788271, 2015). "We observed CCL5 inducing VEGF expression and subsequently promoting angiogenesis and tumor growth through down-regulating miR-200b via PI3K/Akt signaling pathway." (PMID 25301739, 2014). "It is now apparent that RANTES/CCL5 exhibits critical functions in many diverse physiopathological mechanisms, including tumor progression and angiogenesis." (PMID 25260916, 2014). "CAFs produce CCL2, CCL5, CCL7, CXCL8, and CXCL14 and these chemokines promote tumor progression mainly by enhancing the motility of tumor cells." (PMID 24966464, 2014). "Attraction of NK cells is mediated by chemokines, such as CCL5 (or RANTES, binding CCR5), CCL19 and CCL21 (binding CCR7), CXCL10 (binding CXCR3) and CXCL12 (binding CXCR4) that are secreted by other immune cells or the tumor itself." (PMID 24473086, 2014). "Tumour infiltrating macrophages, also indicated as TAMs, derive from circulating monocytic precursors and are recruited to tumour sites by several molecules, such as the chemokines CCL2 and CCL5, VEGF, TGF-β, and colony stimulating factors (GM-CSF and M-CSF)." (PMID 24741617, 2014). "Concomitantly, CD8+ TIL numbers correlate well with the expression of CCL5, a ligand for CCR5, by tumor tissues." (PMID 24966464, 2014). "In CXCL447–70-treated tumors significantly more intratumoral monocytes/macrophages and dendritic cells were present and higher expression levels of CCL5 and IFN-γ were detected by qPCR on tumor lysates." (PMID 25373734, 2014). "Expression of CCL5, CCL3, and CCL19 by OVs enhances chemotaxis of immune cells within the tumor and improves overall therapeutic benefits in vivo." (PMID 24967214, 2014). "Mast cells infiltration is occurred in the tumor microenvironment in a number of human malignancies in response to tumor-derived chemoattractants such as CCL2 and CCL5." (PMID 24455486, 2014). "The levels of the tumor initiators HER2 and KRAS and metastasis genes VEGF, CXCL-4, CCL5, NEDD9 and RHoC were reduced in MCF-7 cells with UBE2C knockdown and increased with UBE2C overexpression." (PMID 24699941, 2014). "In the present study, CCL5 was upregulated in all tumor samples compared to GC B cells, but the upregulation was significant only in THRLBCL tumor cells (1.5-fold upregulation, FDR = 0.037, p = 0.014, t-test)." (PMID 24244368, 2013). "CCR5 deficiency (demonstrated by use of CCR5−/− mice) or CCL5 blockade (using Met-RANTES) led to diminished CD4+Foxp3+ T cells numbers and slower tumor growth." (PMID 23874342, 2013). "Several studies suggest that MSCs promote tumor metastasis though secretion of SDF-1, CCL-5, and other chemokines." (PMID 23744479, 2013). "CCL5 produced by CD4+ T cells activated CC5R+ dendritic cells, eliciting tumor-reactive CD8+ T cell to kill ovarian cancer cells through CD40." (PMID 24213462, 2012). "CCL5 and CCL20 chemokines are also involved in TReg trafficking, and that blockade of those chemokines reduces TReg cells trafficking and inhibits tumor growth." (PMID 22481922, 2012).
tumor (continued). "In contrast to the abundancy of inflammatory infiltrates observed in the lesions of the anti-CCL5-treated animals, such responses were rather poor wihin liver tumors of other treated mice, suggesting that CCL5 blockade may favour immune destruction of the tumor." (PMID 22205974, 2011). "Intrahepatic lymphocytes, isolated from non-tumor tissue, were stimulated with peptides overnight and culture supernatants were screened for CXCL-8, CXCL-9, CXCL-10, CCL-5, CCL-2 as well as IL-17 and the anti-inflammatory cytokine IL-10." (PMID 21876747, 2011). "These proteins, which include CCL5, MAPKs, ERK and DDR1, have been reported to be involved in tumor development." (PMID 22174909, 2011). "Our studies demonstrate that CD4+ T cells expanded against tumor antigen secrete high levels of CCL5, thus promoting the recruitment of CCR5 expressing T cells and DCs to the tumor site." (PMID 21076522, 2010). "We studied the interplay between the tumor cell-derived cytokine regulated-upon-activation, normal T-cell expressed and secreted (RANTES; CCL5) and S100A4 which were shown to be critical factors in tumor progression." (PMID 20442771, 2010). "Some data indicate that chemokines, such as IL-8 (CXCL8), MCP-1 (CCL2), and RANTES (CCL5), not only stimulate migration, but also proliferation of tumor and stromal cells, including endothelial cells." (PMID 18728788, 2008). "Finally, in the CCL network, CCL3 and CCL3L3 produced by MG1, MG2, tumor-cell clusters 4 and 6, oligodendrocytes, and MDM5 engaged CCR1 on MG3, while CCL5—expressed exclusively by MDM5—also targeted MG3." (PMID 41503214, 2026). "The results revealed that irradiation increased the levels of chemokines involved in the migration of T cells (e.g., CXCL10, CCL2, CCL3, and CCL5) but decreased the levels of proangiogenic factors (e.g., VEGF and basic FGF), which facilitate T cells infiltration into the tumor bed." (PMID 40510363, 2025). "Considering the crucial effect of CCL5/CCR5 on the response to cisplatin treatment, we repurpose CCR5 antagonist maraviroc to enhance the chemotherapeutic efficacy of NEPC and observe a remarkable improvement in tumor suppression in the NEPC mouse model." (PMID 41152972, 2025). "The chemokine and receptor profiles of tumor-infiltrating NK1 and NK5 showed increased expression of CCL5, CCL4, XCL1, XCL2, and CXCR3, suggesting that they may be involved in NK tumor homing and activation." (PMID 40315330, 2025). "In the LLC tumor rechallenge murine model, we observed that TCM‐like cells could be further subdivided into four populations based on Ly108 and CCL5 expression." (PMID 39629989, 2025). "Moreover, TLR9-mediated tumor progression involves the implication of various chemokines, particularly CCL2 and CCL5, along with matrix metalloproteinases (MMP), such as MMP-2 and MMP-9." (PMID 41157253, 2025). "Notably, depletion of GPATCH3 led to significant upregulation of CXCL8, CCL5, LAG3, and PVRL2 —genes with well-established roles in immune cell recruitment, immune checkpoint signaling, and tumor–immune interactions." (PMID 40861452, 2025). "In addition, both of these chemokines, as well as CCL5, were relatively decreased in CD8+ T cell–depleted mice for both tumor types." (PMID 40553564, 2025). "Indeed, monocytes/macrophages, neutrophils, and Tregs can be recruited to the tumor via CXCL1 and CCL5 chemokines, the genes for which contain hypoxia-response element sequences." (PMID 40095115, 2025). "Moreover, investigations revealed that in the LLC tumor model, the knockdown of ORMDL3 led to a significant increase in the expression of ISGs, including Ccl5, Cxcl10, Tnf, and Il6, compared to the control group." (PMID 40126553, 2025). "Among them, the chemokine family, including CC (e.g., CCL1, CCL3, CCL5, CCL7, and CCL15), CXC (e.g., CXCL1, CXCL3, CXCL5, and CXCL10), XC (e.g., XCL1 and XCL2), and CX3C (e.g., CX3CL1), plays a pivotal role in tumor development, metastasis, and chemotherapy resistance 30-33." (PMID 40740234, 2025).
tumor (continued). "Moreover, the nuclear translocation of p65/p50 enhanced the transcription of CCL5 and CX3CL1, prompting tumor cells to release more T cell chemokines." (PMID 40995667, 2025). "Additionally, CCL5 promotes epithelial-mesenchymal transition (EMT) via the PI3K/AKT pathway, contributing to tumor progression and immune evasion." (PMID 40396123, 2025). "This study reveals that KMT5C activates DNA damage repair to inhibit STING‐IRF3 pathway, downstream type I IFN signaling and CCL5 secretion, leading to the downregulation of CD8+ T cell infiltration and function in NSCLC, ultimately facilitating tumor progression." (PMID 40126333, 2025). "Furthermore, adipose-derived stem cells (ASCs), under the influence of metastatic cancer cells, produce factors like C-C motif chemokine ligand 5 (CCL5) and alpha-smooth muscle actin (α-SMA), which facilitate tumor angiogenesis and promote cancer progression." (PMID 40149349, 2025). "Moreover, our transcriptomic data further revealed that lacidipine regulated multiple immune‐related genes, significantly upregulating “hot” tumor‐related genes such as CCL5, CD274, CXCL10, and CXCL11, while downregulating the “cold” tumor‐related gene CCL2." (PMID 39585774, 2025). "In contrast, M2-type microglia are activated by anti-inflammatory cytokines, such as IL-4, IL-10, IL-13, and TGF-β, and secrete anti-inflammatory and immunosuppressive factors such as CCL5, TGF-β and MMPs, which facilitate tumor cell proliferation and the establishment of brain metastases." (PMID 41219968, 2025). "Tumor rejection is accompanied by antigen spreading, abscopal effects, and infiltration by clonally diverse T cells, dendritic cells, and MHC I/II+ macrophages producing CXCL9/10, CCL5/8, and TNF." (PMID 41256707, 2025). "Across multiple preclinical tumor models, RT has been shown to increase the expression of cytokines such as IL-1β, GM-CSF (CSF2), and G-CSF (CSF3), along with chemokines including CXCL1, CXCL2, CXCL5, CCL2, and CCL5." (PMID 40805288, 2025). "In addition, we generated a tumor xenograft model in C57BLC/6 mouse, and found that the phenotypes of the shKmt5c mice group were almost rescued by Ccl5 knockdown." (PMID 40126333, 2025). "Furthermore, αPD-L1-γδ T cells remodel the tumor microenvironment to be immune-active, at least partially through the recruitment and activation of CD8+ T cells via the CCR5/CCL5 axis." (PMID 40842867, 2025). "RT has been found to upregulate the expression of specific chemokines, including C–C motif chemokine ligand 5 (CCL5) and C–X–C motif chemokine ligand 9 (CXCL9), which play crucial roles in recruiting and guiding T cells to the tumor site, further improving T‐cell‐mediated tumor control." (PMID 40416596, 2025). "This elevated CCL5 induces MMP9 and VEGF-A, promoting tumor invasion and angiogenesis." (PMID 41445742, 2025). "Chemokines such as C-C motif chemokine ligand 5 (CCL5), C-C motif chemokine ligand 11 (CCL11), C-X-C motif chemokine ligand 9 (CXCL9), and C-X-C motif chemokine ligand 10 (CXCL10) are believed to be primary mediators of eosinophil-driven tumor necrosis." (PMID 40761780, 2025). "Additionally, NK cells secrete chemokines such as CCL1, CCL2, CCL3, CCL4, CCL5, and CXCL8, which contribute to the recruitment of T cells and macrophages into the TME, and tumor cell destruction." (PMID 40141437, 2025). "Particularly, intravesical instillation of VB-85247 induced elevated gene expression in the tumor-bearing bladders for IFNβ, CXCL10, CCL5, IL6, and TNFα at 4 hours after treatment, with the fold-induction of gene expression in the order of IFNβ > CXCL10 > CCL5 > IL6 > TNFα." (PMID 39700406, 2025). "In addition, cGAS-STING activation also promotes the secretion of chemokines (e.g., C-X-C motif chemokine 9 (CXCL9), CXCL10 and C-C motif chemokine ligand 5 (CCL5)), and enables CTL infiltration and tumor recognition." (PMID 40849659, 2025).
tumor (continued). "To assess the functional relevance of these findings, we tested whether knockdown of CCL5 and CXCL2 in tumor cells (OE_shCCL5_shCXCL2) could abrogate the anti-tumor effects of NLRP4-OE." (PMID 40087771, 2025). "USP6 exhibits tumor-suppressive functions in Ewing sarcoma by enhancing immune activation and chemokine production (such as CXCL10 and CCL5), which could counteract tumor growth." (PMID 40348771, 2025). "Furthermore, infiltration of αPD-L1-γδ T cells shaped the immunoactive tumor microenvironment (TME), at least partially through the recruitment and activation of CD8+ T cells via the CCR5/CCL5 axis." (PMID 40842867, 2025). "Tumor-associated macrophages (TAMs) derived from blood monocytes, myeloid-derived suppressor cells, and tissue resident macrophages are induced and differentiated in tumor tissues by cytokines such as C-C motif chemokine ligand 2 (CCL2), CCL5, and colony-stimulating factor 1 (CSF-1)." (PMID 41002446, 2025). "Given the potential relevance of this response regarding tumor immunogenicity, and eventually for leveraging the efficacy of ICI-based therapies, we validated the effect of CM272 on the expression of chemokine CCL5 and different MHC genes such as HLA-A, HLA-B and HLA-C." (PMID 39810240, 2025). "Thus, chemokines such as CX3CL1, CCL5, and CXCL1 are involved in the actions of EVs-mediated premetastatic niche formation, enhanced tumor invasion, and modulated immune responses." (PMID 40103824, 2025). "It is widely acknowledged that chemokines secreted by tumor cells such as CCL2, CCL5, CCL7, CCL20, CXCL2, CXCL8 and CXCL12 significantly contribute to the recruitment of monocytes and macrophages during neoplastic transformation, among which CCL2 plays a key role in TAM recruitment." (PMID 40380196, 2025). "Moreover, in miR-29 overexpressing tumors, there were significant changes in cytokine and chemokine expression, such as upregulation of CCL5, CCL11, CXCL9, CXCL11, and CXCL16, known for their anti-tumor effects." (PMID 38890285, 2024). "Indeed, anti-tumor immunity in MMRd cancers also depends on the magnitude of cGAS/STING activation and subsequent expression of CCL5 and CXCL10 in the tumor microenvironment (TME), which influences CD8+ T and NK cell infiltration." (PMID 39544936, 2024). "Additionally, we observed upregulation of IL-1β target genes IL-8, VEGF, CCL5, and MMP2 in SUM159, MCF12A and MDA-MB-231 cells This upregulation indicates functional activation of IL-1β signaling in tumor cells co-cultured with B cells." (PMID 39801513, 2024). "Moreover, it is possible that CCL2, CCL5, CCL18, TGFB1, and GDF15 are also produced by cells other than the VS tumor cells." (PMID 39272860, 2024). "Furthermore, EPI treatment effectively accelerated the secretion of Ccl5 and Cxcl10, promoting the recruitment of CD8+ T cells into the tumor." (PMID 38622609, 2024). "Together, these findings highlight the disruption of the tumor microenvironment in AIP-mutant-positive tumors and suggest that CCL5 and its receptor CCR5 could serve as potential therapeutic targets." (PMID 38479600, 2024). "Our results might suggest an influence of the immunomodulatory cytokines CCL5, CCL18, GDF15, and TGFB1 on tumor progression." (PMID 39272860, 2024). "The study indicated that the anti-tumor immune responses following DDR targeting were observed to be mediated through the STING–TBK1–IRF3 pathway in SCLC, which stimulated secretion of the chemokines CCL5 and CXCL10." (PMID 38473324, 2024). "This shift from CCL5/CXCL9/CXCL10 to CXCL8/CXCL12/CCL22 production was attributed to NFκB-mediated induction of COX2/PGE2/EP4, along with upregulation of IDO1 and IL-10, further contributing to the immunosuppressive tumor microenvironment." (PMID 39409924, 2024). "Unlike CCL2, the release of CCL5 by tumor cells not only promotes TAMs and MDSCs infiltration, participating in tumor metastasis,but also recruits CD8 + T cells to enhance adaptive immunity." (PMID 38528587, 2024).